INS (insulin)
Diseases named in the same sentence as INS in open-access papers (continued):
Sharing a sentence is not in itself a finding about the gene and the disease.
Insulin resistance (continued). "Research in this regard has focused on the relationship between the degree of adiposity and a greater or lesser probability of developing insulin resistance; however, there is evidence of subjects with extreme obesity who retain insulin sensitivity." (PMID 35682723, 2022). "In fact, independently on their A, B or C phenotype, metabolic alterations were related to body weight with obese patients of the three phenotypes presenting elevated insulin levels, increased insulin resistance, and altered lipid profiles." (PMID 36292002, 2022). "Findings from previous studies indicate a significant reduction in fasting insulin levels or an improvement in insulin resistance following the nuts consumption in both healthy and diabetic individuals." (PMID 35425791, 2022). "Elevated insulin levels in the portal system are the initial manifestation of insulin resistance, and later peripheral insulin levels increase." (PMID 35586622, 2022). "Insulin resistance in endothelial cells plays an important role in atherosclerosis by reducing insulin signaling through the Akt/eNOS pathway." (PMID 35457157, 2022). "Our previous study has shown that GPT ameliorates metabolic abnormalities and insulin resistance by enhancing insulin signaling in skeletal muscle of Zucker fatty rats." (PMID 36547073, 2022). "Normal pregnancy is critically dependent on the development of maternal insulin resistance and an increased capacity to secrete insulin, which allows for the allocation of nutrients for fetal growth." (PMID 36239315, 2022). "Glimepiride is a long-acting sulfonylurea oral hypoglycemic agent, which can improve insulin resistance and insulin sensitivity by stimulating pancreatic β cells to secrete insulin." (PMID 35571731, 2022). "Macrophages appear to be the principal source of pro-inflammatory cytokines such as IL-1β and TNFα that can confer insulin resistance in insulin-sensitive cells." (PMID 35955975, 2022). "Supporting the relevance of these mouse studies to humans, insulin replacement therapies induce insulin resistance in people with Type-1 diabetes." (PMID 34823065, 2022). "This intervention showed that zinc supplementation reduces LDL, Total Cholesterol, C-reactive protein (CRP), markers of insulin resistance, fasting blood sugar, insulin, and Homeostatic Model Assessment for Insulin Resistance (HOMA-IR) in children." (PMID 36017230, 2022). "ALA also improved serum insulin levels in patients with NAFLD by reducing insulin resistance in two recent double-blind, placebo-controlled, randomized clinical trials, and increased serum H2S levels, leading to improved glycemic status in T2DM patients." (PMID 36229864, 2022). "The prolonged ingestion of an HSD results in decreased insulin production (reduced Dilp2, 5) and increased insulin resistance, indicating a type 2 diabetes phenotype." (PMID 35204721, 2022). "Mounting evidence has shown that activation of SIRT1 can improve insulin sensitivity in the liver and adipose tissues and improve insulin resistance." (PMID 35739982, 2022). "In particular, n-6 long-chain PUFAs play an important role in insulin resistance and hyperlipidemia by affecting the production of inflammatory factors and the binding of insulin to its receptor on the cell membrane." (PMID 35898714, 2022). "It is believed that insulin resistance leads to hyperinsulinemia because of excessive production of insulin by β-islets in an effort to control the blood glucose." (PMID 36434695, 2022). "It is well known that acute insulin resistance in humans is followed by hyperglycemia, as both the inability of insulin to adequately stimulate glucose uptake, mainly into skeletal muscle, and the inhibition of gluconeogenesis in the liver occur." (PMID 35897684, 2022). "As anticipated, women with GDM had higher concentrations of insulin and evidence of insulin resistance but clinically comparable results in relation to a standard full lipid profile." (PMID 35359001, 2022).
Insulin resistance (continued). "In type 2 diabetes, individuals develop insulin resistance in the peripheral target tissues, thereby prompting a high demand for insulin from the overexerted beta cells of the pancreas." (PMID 36290804, 2022). "Insulin resistance is one of the key pathophysiological factors for developing T2D, and approaches to manage T2D include measures to improve insulin sensitivity, such as physical activity." (PMID 35684094, 2022). "Data on insulin levels were also unavailable, and indices of insulin resistance and beta-cell dysfunction were unable to be calculated." (PMID 35392888, 2022). "HOMA-IR is calculated using fasting glucose and insulin and used to approximate insulin sensitivity, with values above 2.0 indicating insulin resistance." (PMID 36296997, 2022). "The products of the PI-cycle diacylglycerol (DAG) and phosphatidylinositol 3,4,5 triphosphate (PIP3) are important mediators of insulin signaling and insulin resistance." (PMID 36038539, 2022). "It directly inhibits the expression of PPAR-γ, insulin signaling, and glucose tolerance, leading to cellular and systemic insulin resistance and glucose intolerance." (PMID 35832790, 2022). "Second, insulin resistance, which plays a key role in the development of fatty liver disease, leads to excessive insulin secretion in the blood." (PMID 35061826, 2022). "The IL-6 contributes to inflammation in all insulin target tissues, including fat, the liver, and muscle, indicating the role of IL-6 in driving obesity and in the pathogenesis of systemic insulin resistance." (PMID 35846757, 2022). "The inflammatory cytokines produced by M1 macrophages neutralize the insulin-sensitizing actions of the hormones adiponectin and leptin, which eventually lead to insulin resistance." (PMID 36466412, 2022). "COVID-19 direct injury to human islet cells, determining beta cell damage and the endogenous insulin secretion’s reduction, as well as the cytokine storm, lead to insulin resistance." (PMID 36278672, 2022). "Its activity is mainly mediated via protecting islet cells, promoting insulin secretion or release, improving insulin resistance and promoting sugar utilisation by peripheral tissues and organs." (PMID 36091757, 2022). "Insulin secretion is increased temporarily in these patients, presumably to compensate for the onset of insulin resistance in the short term." (PMID 35216514, 2022). "HOMA-IR based on insulin and glucose was developed as a convenient method for measuring insulin resistance, which reflected insulin resistance mainly in the liver." (PMID 35260102, 2022). "It was demonstrated that reduction of miR-128-3p level would preserve insulin-stimulated glucose uptake in cardiomyocytes, and mitigate myocardial insulin resistance." (PMID 36209049, 2022). "Insulin resistance consists of a reduced sensitivity of cells to insulin molecules, which results from the compensatory increase in insulin secretion by pancreatic islets during chronic hyperglycemia." (PMID 35348048, 2022). "It is known however, that central insulin resistance or a lack of insulin signalling in the brain following a meal leads to alterations in appetite control and changes in food satiation." (PMID 35860945, 2022). "Considering that inflammation is associated with the development of insulin resistance in neurons, we evaluated the effect of MCM-induced inflammation on insulin signaling in mHypoA-2/29 cells." (PMID 35883638, 2022). "T2DM is a complex chronic disorder highly prominent in older people, characterized by the chronic increase in blood glucose levels, impaired insulin secretion by pancreatic β-cells, and insulin resistance." (PMID 35600880, 2022). "Significant improvements in serum insulin, the Homeostatic Model Assessment for Insulin Resistance (HOMA-IR) index, and resistin levels were also observed in the DIO mice." (PMID 35805168, 2022).
Insulin resistance (continued). "The insulin tolerance test pre-supplementation showed that the DIO group had lower insulin sensitivity than the control group, showing installation of insulin resistance." (PMID 35889863, 2022). "Insulin resistance is common in obesity, which means that the sensitivity of the liver, muscles, and fat cells to insulin is reduced." (PMID 36345438, 2022). "Current therapies aim to improve insulin resistance (metformin), enhance pancreatic insulin output (meglitinides, sulfonylureas, GLP-1 analogs), or prevent reabsorption of glucose into the blood through the kidneys (SGLT2 inhibitors)." (PMID 36030052, 2022). "Initially, to compensate for insulin resistance in vivo, more insulin is secreted by the endocrine pancreas to enhance peripheral glucose utilization." (PMID 35432196, 2022). "This study aims to explore the effects of protein intake from different sources on maternal insulin secretion and insulin resistance by combining population and animal studies." (PMID 36501068, 2022). "In individuals with insulin resistance, insulin‐stimulated glucose uptake is reduced significantly in skeletal muscle leading to the development of atrophy." (PMID 35088922, 2022). "The idea of insulin resistance was firmly established among clinicians by the early 1940′s who had observed that there were rare patients who required large doses of insulin to control blood sugar." (PMID 35884888, 2022). "Mirroring these findings, a mouse model of NS-ML, expressing a hypoactivating mutation of SHP2 (SHP2 T468M/+), displayed insulin hypersensitivity and protection to HFD-induced insulin resistance, although it shares with NS the reduced adiposity." (PMID 36140242, 2022). "Our analyses suggested that the plasma insulin levels decreased as insulin resistance was relieved by HMC or RG supplementation." (PMID 35565920, 2022). "Hyperglycemia in T2D can result from insulin resistance, lower insulin secretion, and/or reduced β-cell mass." (PMID 36461078, 2022). "The insulin resistance also leads to weaker insulin antilipolytic effect and fatty acid metabolism resulting in an increased release of free fatty acids (FFA)." (PMID 33671850, 2021). "Decreasing plasma insulin level and improving insulin resistance in patients with PCOS not only benefit hyperandrogenism and ovulation but also reduce cardiovascular risks." (PMID 33669954, 2021). "The chronic inflammation is an important determiner of insulin resistance 120, so the protective role of MSCs in improving insulin sensitivity via suppressing the inflammatory activity has been focused." (PMID 33897874, 2021). "The association of adiponectin with insulin resistance was first established by Yamauchi and colleagues in 2001 when reduced adiponectin levels and insulin resistance was observed in mouse models with altered insulin sensitivity." (PMID 33897460, 2021). "Glucose tolerance and insulin sensitivity were improved in high-fat diet mice and diabetic mice—two models of insulin resistance—and insulin resistance was decreased after treatment with S. spinosum." (PMID 33572627, 2021). "It has been noticed that women with high serum ferritin levels have a strong relationship with GDM by increased insulin resistance and increased insulin secretion from the pancreas resulting in pancreatic beta-cell exhaustion." (PMID 34722008, 2021). "In the present study, potential molecular biomarkers of NASH hepatocarcinogenesis were investigated using the STAM mice NASH model, characterized by impaired insulin secretion and development of insulin resistance." (PMID 33802238, 2021). "Another study showed that, particularly in women, VAT was associated with insulin resistance and insulin secretion, and that in men, both VAT and SAT were associated with insulin resistance to a similar extent." (PMID 34869524, 2021). "In patients with obesity, insulin signal transduction is impaired, leading to insulin resistance and increased HOMA-IR levels." (PMID 33883996, 2021).
Insulin resistance (continued). "These two methods use fasting insulin and glucose concentrations to measure insulin resistance, and the results correlate well with the values reported in clamp studies." (PMID 33402193, 2021). "GLP-1 is an intestinal insulin-stimulating peptide that has several functions, such as lowering blood sugar and improving insulin resistance." (PMID 33868571, 2021). "After insulin resistance induction by palmitic acid (16:0), the appropriate phospholipid derivatives were added to insulin-resistant cells and cultured for an additional period of 48 h." (PMID 34684619, 2021). "The liver account for 30% of insulin-stimulating glucose and insulin resistance can lead to an increased triglycerides content and very-low-density-lipids (VLDL) secretion." (PMID 33673200, 2021). "The mechanism of androgen-related insulin resistance is related to a decrease in expression of adipokines, including adiponectin and omentin-1, which are beneficial to insulin sensitivity in the mouse model of PCOS." (PMID 34987473, 2021). "Lipoprotein lipase, a key enzyme in the elimination and breakdown of TGs from the circulation, enzyme is alleviated by both insulin deprivation and insulin resistance." (PMID 34290966, 2021). "Second, women have a greater capacity for insulin secretion and are less prone to insulin resistance than men." (PMID 35003255, 2021). "Preclinical rodent models of cancer also recapitulated the reduced blood-glucose-lowering effect of insulin, finding insulin resistance and glucose intolerance compared to controls." (PMID 33801684, 2021). "Feeding rats with a high-fat diet promotes the development of obesity and insulin resistance, while injection of streptozotocin selectively destroys pancreatic β-cells and, thus, impairs insulin secretion." (PMID 34439892, 2021). "In the late postprandial period, IGF-I attenuates GH-mediated insulin resistance, while it reduces insulin secretion by the pancreas." (PMID 34360563, 2021). "The main characteristic of the disease is the appearance of insulin resistance, which is a defect in insulin signaling and a correct coupling of insulin with its receptor." (PMID 34069890, 2021). "The Matsuda index, a combination of parameters derived from a fasting and postprandial insulin assay, is an early biomarker for metabolic dysregulation (i.e. insulin resistance/compensatory hyperinsulinemia)." (PMID 33859227, 2021). "To summarize, our results demonstrate that calystegines from Hyoscyamus albus provide cytoprotection to the HepG2 cells against insulin/glucose induced insulin resistance and apoptosis due to activation of PI3K/AKT and SIRT1/NF-kB/JNK signalling pathways." (PMID 34034759, 2021). "Nevertheless, in future studies, it would be worth determining other parameter characterizing insulin resistance (such as fasting insulin and HOMA-IR index) to evaluate the specific role of NPQ in carbohydrate dysfunctions." (PMID 34944507, 2021). "Pioglitazone is a potent insulin sensitizer that targets PPARγ signaling to decrease systemic and myocardial insulin resistance, with favorable effects on cardiac metabolism." (PMID 33604337, 2021). "TNF-α is involved in insulin resistance in obese animals and can damage insulin function, which down-regulates glucose transporter-4 (GLUT4) expression and action during glucose metabolism and enhances lipolysis." (PMID 34443619, 2021). "The ginger group also had reductions in insulin, glucose, insulin resistance, LDL-C, and triglycerides and increases in HDL-C and HDL-C/LDL-C compared to baseline." (PMID 34239993, 2021). "Participants’ glucose metabolic health status was determined based on fasting plasma glucose, insulin, homeostasis model assessment of insulin resistance (HOMA-IR), glycated hemoglobin (HbA1c), and 2-h postload glucose." (PMID 34966358, 2021).
Insulin resistance (continued). "There were no significantly statistical differences in the age, active physical activity level, BMI, WC, 2hPG, TC, TG, LDL-C, SBP, DBP, fasting insulin, homeostatic model assessment-insulin resistance (HOMA-IR) or serum creatinine between these two groups." (PMID 34847893, 2021). "In animal studies, it was shown that insulin resistance, in which insulin levels are supraphysiological, leads to decreased bone turnover and therefore, a tendency of a high BMD." (PMID 34574647, 2021). "Increased fasting insulin levels/insulin resistance were seen at the end of the antibiotic pulses and the end of the study in ABT males." (PMID 33445530, 2021). "Comparative analysis of the variables between the study terms revealed a marked decrease in the concentration of 25(OH)D (p ≤ 0.0001), insulin (p < 0.05), insulin resistance index (HOMA-IR), (p < 0.05)." (PMID 34035990, 2021). "Insulin resistance is one of the major pathogenic mechanism of T2DM and metformin action is directed to the improvement of insulin sensitivity, especially in the liver and muscle." (PMID 33562458, 2021). "Propolis reduced serum levels of HbA1c by ~11%, insulin by ~46%, homeostasis model assessment of insulin resistance (HOMA-IR) by ~39%, homeostasis model assessment of β-cell function (HOMA-β) by 42%, and serum TNF-α by ~30%." (PMID 33652692, 2021). "We previously demonstrated that the plasma PAI‐1 levels, but not the leptin levels, of obese Japanese children were also significantly correlated with insulin resistance indexes, such as the immunoreactive insulin (IRI), HOMA‐R and QUICKI values." (PMID 33532616, 2021). "The L14 extract is the most salutary for obesity and insulin sensitivity and has a greater ability to attenuate adipogenic differentiation and obesity-induced insulin resistance among the three new L. plantarum extracts." (PMID 33954196, 2021). "In research studies, concurrent insulin measurement can be performed to assess insulin resistance and β cell function." (PMID 34022907, 2021). "In summary, glucose metabolism dysfunction in the form of hyperinsulinemia, insulin resistance, hyperglycemia, and altered insulin signaling are all metabolic factors that can be individually and holistically linked to Aβ metabolism, and therefore AD risk." (PMID 34497507, 2021). "To confirm that chronic exposure to a HFD for 8 weeks would promote insulin resistance in our animal model, we measured body weight, glycemia, and plasma insulin in obese and control mice." (PMID 34638553, 2021). "Our study indicated that RSV is beneficial for improving insulin resistance, so we tested the key molecules of the insulin signaling pathway and genes related to lipogenesis, fatty acid oxidation, and fatty acid uptake." (PMID 33708180, 2021). "By way of conclusion, to our best knowledge, the L-IDE-KO is one of the few knockout mice models of hepatic insulin resistance in which insulin clearance has been assessed in normal and HFD feeding." (PMID 33477364, 2021). "The systemic inflammation, pancreatic β-cells disfunction, and defect in insulin signaling pathway are engaged in insulin resistance and T2D development." (PMID 34684492, 2021). "Insulin resistance is a condition that arises from the defect in insulin-mediated actions on glucose and lipid metabolism, which occurs mainly in liver, muscles, and adipose tissues." (PMID 34946711, 2021). "In muscles, a major site of glucose utilization, insulin resistance reduces glucose uptake and this will induce a compensatory increase of insulin secretion and hyperinsulinemia." (PMID 33669443, 2021). "Expression of the active form of Drp1 in the DVC induced insulin resistance and impaired the insulin-dependent decrease in food intake in RC-fed rats." (PMID 33227495, 2021). "In HIV-infected subjects, FGF21 levels showed a strong positive correlation with triglycerides, insulin levels and insulin resistance with a p-value <0.0001." (PMID 34019585, 2021).